EGFR (epidermal growth factor receptor)
Diseases named in the same sentence as EGFR in open-access papers (continued):
Sharing a sentence is not in itself a finding about the gene and the disease.
lung cancer (continued). "Our observation will pave the way for future drug development using metformin to address the resistance to EGFR TKIs and may lead to better lung cancer therapy in both metastatic and adjuvant settings." (PMID 35070958, 2021). "Radioresistant human lung carcinoma cells treated with erlotinib or cetuximab EGFR inhibitors." (PMID 34900673, 2021). "Finally, we only carried out experiments using A549 cells, which acted as surrogate tissue for KRAS mutant/EGFR wild type lung carcinoma." (PMID 34858801, 2021). "Conversely, the tumour suppressors CMTM3 and CMTM7 (chemokine-like factor-like MARVEL transmembrane domain-containing 3 and 7) inhibit EGFR-mediated tumorigenicity and EGFR-dependent cell migration by stimulating Rab5 activity, in gastric and lung carcinomas, respectively." (PMID 34831480, 2021). "These complexes exhibited 10-fold higher EGFR-inhibiting activity than the clinically used EGFR inhibitor and anticancer drug gefitinib and potent antiproliferation activity against a panel of tumor cell lines, especially lung cancer." (PMID 32411653, 2020). "The designed compound (21a) might serve as an encouraging lead compound for the discovery of promising anti-lung cancer agents targeting EGFR/HER2." (PMID 33374155, 2020). "Unlike cancers driven by KRAS mutations, many EGFR inhibitors have been used in the treatment for lung cancers, including Erlotinib (Tarceva), Afatinib (Gilotrif), Gefitinib (Iressa), Osimertinib (Tagrisso), Dacomitinib (Vizimpro), and Necitumumab (Portrazza)." (PMID 32308773, 2020). "According to the National Comprehensive Cancer Network (NCCN) Guidelines for nonsmall cell lung cancer, NSCLC patients in advanced stages showing the EGFR mutations are treated with epidermal growth factor receptor (EGFR) tyrosine kinase inhibitors as molecular target therapy." (PMID 33167343, 2020). "Owing to osimertinib efficacy on brain metastases demonstrated in large Phase 3 trials in patients with or without T790M mutation, osimertinib should also be considered the first-line treatment of choice in EGFR-mutant lung cancer patients with choroidal metastases." (PMID 33272243, 2020). "Besides, this combination therapy can reverse EGFR-tyrosine kinase inhibitor (EGFR-TKIs) resistance in lung cancer." (PMID 32723346, 2020). "By selecting EGFR-TKI resistant lung cancer cells in vitro, we could monitor changes in CEA heterogeneity in CEA-positive lung adenocarcinoma cells during gefitinib treatment." (PMID 32034239, 2020). "Notably, the combination of a first-generation EGFR TKI plus dasatinib was evaluated in a phase II clinical trial in patients with EGFR-mutant lung cancer and acquired resistance to either gefitinib or erlotinib." (PMID 32404161, 2020). "An end-to-end efficacy evaluation approach for identifying progression risk after epidermal growth factor receptor (EGFR)–tyrosine kinase inhibitor (TKI) therapy in patients with stage IV EGFR variant–positive non–small cell lung cancer (NSCLC) is lacking." (PMID 33331920, 2020). "While lung cancer patient outcomes are well-recognized to vary as a function of patient sex, there has been insufficient research regarding the relationship between patient sex and EGFR(Epidermal growth factor receptor) response efficacy." (PMID 33075110, 2020). "NSCLCs are the main kind in the lung cancer, and EGFR-positive NSCLC is a common type in the NSCLC." (PMID 32256661, 2020). "First, EGFR mutation was usually obtained at the diagnosis of lung cancer, rather than at the initiation of immunotherapy." (PMID 33067442, 2020). "A potential relationship may also exist between PD-L1 expression and EGFR-TKI efficacy in EGFR-mutant lung cancer patients." (PMID 33363040, 2020). "Thus, acquired EGFR‐TKIs resistance promotes the immune escape of lung cancer by upregulating the expression of PD‐L1." (PMID 32875727, 2020).
lung cancer (continued). "EGFR-mutant lung cancers are one of the most frequent molecularly defined subsets accounting for approximately 40% in East Asians with lung adenocarcinoma, and agents targeted EGFR have been the first-line therapy for NSCLC patients with EGFR mutation." (PMID 32595734, 2020). "Given that aberrant EGFR signaling is a significant driver of lung cancer and that approximately 50% of Asian patients with NSCLC harbor EGFR mutations, we further investigated whether BASP1 regulates EGFR signaling." (PMID 33042262, 2020). "However, another study has shown significant anti-tumour activity of osimertinib in xenograft models of the WT EGFR lung cancer cell line H2073 cells engineered to express either D770_N771insSVD or V769_D770InsASV insertions using CRISPR." (PMID 31562956, 2020). "The EMT leads to increased aggressiveness of the EGFR mutant lung cancer cells." (PMID 33291316, 2020). "The PATH panel was designed to cover most targetable mutations and amplifications for lung cancer, colorectal cancer, melanoma, and GIST for first line treatment options, as well in the setting of therapy resistance (e.g. EGFR, ALK and KIT gatekeeper mutations)." (PMID 32264863, 2020). "In lung cancer, Cav-1 is found to act on multiple downstream effectors, such as epidermal growth factor receptor (EGFR), extracellular regulated protein kinases (ERK), focal adhesion kinase (FAK) and protein kinase B (AKT), to mediate key aspects of cancer progression." (PMID 31991790, 2020). "TYMS played an essential role during the DNA synthesis, the alteration of TYMS might increase the risk of lung cancer, and the expression of TYMS confirmed the correlation with EGFR mutation in LUAD patients." (PMID 32684932, 2020). "Degradation of Mcl-1 overcome acquired resistance to osimertinib in EGFR-mutant lung cancer." (PMID 32276600, 2020). "A study by the Galician Lung Cancer Group showed that OS was higher in patients without an EGFR mutation than in patients with EGFR-mutated NSCLC (12.8 versus 4.8 months, p = 0.12)." (PMID 32708936, 2020). "Clinical data have shown that PD‐1 antibodies are not effective in treating EGFR mutation‐positive lung cancer patients." (PMID 32391629, 2020). "Therefore, simultaneously blocking BASP1 and EGFR signaling with EGFR tyrosine kinase inhibitors were expected to suppress the metastasis of lung cancer cells by suppressing calcium influx." (PMID 33042262, 2020). "We hypothesize that the suppressive activity of RPE against lung cancer cell proliferation and early metastasis occurs via the EGFR-MAPK and mTOR-Akt signaling pathways." (PMID 33158043, 2020). "In NSCLC, EZH2 inhibitors could effectively enhance the sensitivity to etoposide in patients with BRG1- and EGFR-mutant lung cancers." (PMID 33276757, 2020). "Therefore, they can be easily applied to lung cancer decision-making where, if a genetic alteration is revealed to be actionable (e.g., EGFR exon 19 deletion), then an appropriate TKI (e.g., osimertinib) would be given." (PMID 32560187, 2020). "In an early phase II clinical trial for neratinib (NCT00266877), despite disappointing results for EGFR mutant lung cancer overall, three out of four patients with the rare EGFR mutation G719X showed a partial response to neratinib, whilst the fourth exhibited stable disease for 40 weeks." (PMID 31562956, 2020). "The canonical EGFR exon 19 deletion is the most common cancer-linked driver mutation in lung cancer in never smokers." (PMID 31940362, 2020). "In this regard, Jakobsen and coworkers reported that the EGFR is highly expressed on the exosomal surface by analyzing the extracellular vesicles secreted by lung cancer cells, indicating that the EGFR is a promising biomarker for diagnosing non-small cell lung cancer (NSCLC)." (PMID 33396739, 2020).
lung cancer (continued). "Many recent studies have reported that patients with lung cancer and BMs harboring EGFR mutations exhibit improved survival over patients without the mutations due to higher response rates to whole-brain radiation therapy and specific chemotherapy medications." (PMID 32483122, 2020). "With the known role EGFR activation and localization to the mitochondria has in lung cancer cells, evaluating the impact matrix Fibulin-1 could have in mediating mitochondrial function would be of much interest." (PMID 32719793, 2020). "Co‐expression of EGFR and its ligands is commonly found in primary lung cancer." (PMID 32337844, 2020). "Inhibition of key signal mediators downstream of EGFR may have clinical effects in the treatment of lung cancer with EGFR activity." (PMID 32552717, 2020). "Here, we developed a novel diagnostic system named the “EGFR impact score” which is based on multiplex mRNA expression profiles, which can predict the impact of the EGFR pathway in lung cancer cells and the effect of EGFR-tyrosine kinase inhibitors on malignancy." (PMID 32277151, 2020). "This study is the first to prospectively evaluate the utility and feasibility of plasma circulating tumor DNA to detect EGFR mutations in frail patients with lung cancer, when tissue biopsy was not feasible." (PMID 31991049, 2020). "Actually, a previous report has screened almost 600 herbal and natural compounds and found that CUR could promote EGFR degradation to potentiate the inhibitory effect of gefitinib on gefitinib-resistant lung cancer cells in vitro and in vivo." (PMID 32188144, 2020). "Additionally, mutations in the KRAS, BRAF, and PIK3CA genes have emerged as an important predictive marker of resistance to epidermal growth factor receptor (EGFR)-targeting monoclonal antibodies or tyrosine kinase inhibitors in colorectal and lung cancers." (PMID 33054840, 2020). "Hence, a study in NSCLC cell lines harboring EGFR wild type has shown that gefitinib promotes autophagy and apoptosis, leading to lung cancer cell death, via blockade of the PI3K/AKT/mTOR pathway." (PMID 32190291, 2020). "However, the utility of AURKA inhibitors in EGFR mutant lung cancer exceeds this specific molecular context." (PMID 32292420, 2020). "Finally, serum levels of HGF have been associated with resistance to EGFR inhibitors in KRAS wild-type metastatic colorectal cancer and lung cancer." (PMID 32545260, 2020). "In addition, further researches about the role of mucins in lung cancer with different mutational background such as K-ras, EGFR, and BRAF are necessary to guide the combination therapy and overcome drug-resistance for lung cancer." (PMID 32807223, 2020). "In contrast to chemotherapy, Keytruda® (pembrolizumab) significantly prolongs patient survival in patients with lung cancer who have high expression level of PD-L1 (PD-L1 ≥ 50%) and no EGFR or ALK mutations." (PMID 32148531, 2020). "Targeted therapy has provided a positive outcome for lung cancer patients with epidermal growth factor receptors (EGFR), anaplastic lymphoma kinase (ALK), ROS proto‐oncogene 1 receptor tyrosine kinase (ROS1) and B‐Raf proto‐oncogene serine/threonine kinase (BRAF) mutations." (PMID 31975535, 2020). "Osimertinib is a third-generation EGFR-TKI that was developed to address this issue, and the AURA3 study revealed that it provided significantly longer PFS compared to platinum-based chemotherapy among patients with T790M-mutated lung cancer." (PMID 32517152, 2020). "In conclusion, the data suggest that TIMP-3 rs9862 polymorphisms may contribute to identify subgroups of lung cancer patients at high risk for tumor progression, among carriers of LADC-bearing mutant EGFR." (PMID 33126605, 2020). "Currently, many nomograms have been proven to be effective in lung cancer, such as the EGFR mutation model and noncytotoxic chemosensitizer model." (PMID 32282333, 2020). "EGFR-TKIs are widely used in the therapy for lung cancer patients, especially NSCLC patients." (PMID 31892990, 2020).
lung cancer (continued). "Furthermore, IGF-1R expression was shown to be activated in cancers that are resistant to EGFR inhibitors, including lung cancer." (PMID 33198090, 2020). "For example, AGR3 has been shown to facilitate the stemness of colorectal cancer by regulating Wnt/β-catenin signaling; STC2 has been shown to be involved in resistance to treatment with EGFR tyrosine kinase inhibitors and to promote the progression of lung cancer by regulating JUN/AXL signaling." (PMID 33680908, 2020). "Changes in expression patterns of serum carcinoembryonic antigen at initial diagnosis (CEAIn) and disease progression (CEAPd) in lung cancer patients under EGFR-tyrosine kinase inhibitors (TKI) treatment may reflect different tumor progression profiles." (PMID 32034239, 2020). "We found that lower lobe location and a lower expression of EGFR mutations were the independent factors linked to poor prognosis regardless of important clinical factors including lung cancer stage." (PMID 32913267, 2020). "In addition, previous studies have shown that NOTCH-1 can regulate EGFR expression in lung cancer cells." (PMID 32655137, 2020). "Exposure of HCT116 and SW480 colorectal cancer cells to patchouli alcohol activated p21 expression and inhibited the expression of cyclin D1 and CDK4 and induced cell apoptosis and cell cycle arrest in A549 lung cancer cells in vitro and in vivo via the EGFR-MAPK pathway." (PMID 32963578, 2020). "Lee and co-workers have reported the detection of mutations in exon 19 and exon 21 of the epidermal growth factor receptor (EGFR) isolated from both the lung cancer cell lines and the cancer tissues of patients with non-small-cell lung cancer." (PMID 32082965, 2020). "In summary, we identified a novel miR-1-FAM83A axis could partially modulate the EGFR/choline phospholipid metabolism signaling pathway, which suppressed lung cancer growth and motility." (PMID 33266425, 2020). "Two patients with EGFR mutations had early-stage lung cancer and did not receive adjuvant treatment." (PMID 32294880, 2020). "EGFR‐mutated lung cancers are often sensitive to EGFR‐TKI.[[qv: 13]] However, EGFR mutations are not common in PDAC." (PMID 32274304, 2020). "To test the possible role FBLN1 isoforms could have in regulating EGFR signaling and function in lung cancer, we performed siRNA mediated knockdown of FBLN1C and FBLN1D in NSCLC Calu-1 cells." (PMID 32719793, 2020). "This release of IL-1β by macrophages exerts a tumor-promoting effect, which may help explain target therapy-related tumor progression in EGFR mutant lung cancer patients." (PMID 31649305, 2020). "Furthermore, two anti-EGFR sdAbs (aEG2E12 and aEG4D9) were tested for their anti-tumor effect in vivo, and inhibited tumor growth in a lung cancer mouse model." (PMID 33023595, 2020). "Lung cancer patients easily develop resistance to not only conventional chemotherapy drugs, but also molecular targeted drugs, such as epidermal growth factor receptor tyrosine kinase inhibitors (EGFR‐TKIs)." (PMID 32391938, 2020). "IL-6, JUN, EGFR, and MYC were shown to associate with the survival of lung cancer patients." (PMID 32595734, 2020). "Although tyrosine kinase inhibitors (TKI) have shown remarkable benefits against lung cancer, they are not effective for epidermal growth factor receptor (EGFR) mutation-negative patients." (PMID 32899191, 2020). "This supports prior investigation showing no prognostic value of EGFR mutation in early stage lung cancer." (PMID 32523650, 2020). "Another study showed that while inhibition of EGFR led to significant cell death in EGFR-mutant lung cancer cells, it increased stemness properties, e.g., higher ALDH+ population and increased clonogenicity, which was likely driven by an increase in Notch 3 expression." (PMID 32575680, 2020). "Any malignant transformation of EGFR may lead to the spread of lung cancer, so EGFR as a target has become the main research scheme to inhibit the metastasis of NSCLC." (PMID 33262947, 2020).
lung cancer (continued). "Activating EGFR mutations occur in 10–30% of lung adenocarcinomas and are the major cause of lung cancer in never-smokers." (PMID 32897190, 2020). "EGFR is overexpressed in lung cancer and is associated with poor prognosis." (PMID 32719793, 2020). "Additionally, pharmacological experiments indicated that knocking down LINC00152 and blocking EGFR have synergic effects on inhibiting lung cancer progression." (PMID 32774169, 2020). "However, they also found if a non-EGFR mutant lung cancer patient was treated with targeted drugs such as gefitinib, the progression-free survival of the patient would be significantly shorter than those with first-line standard chemotherapy drugs." (PMID 33117680, 2020). "Moreover, metformin significantly delayed and reversed acquired resistance to EGFR TKIs as well as suppressed lung cancer stemness." (PMID 33014814, 2020). "This mutation is rare, but EGFR is considered to be a major cancer predisposition gene, associated with an estimated 31% risk of lung cancer development in non-smoking carriers." (PMID 32104210, 2020). "In Asian SqCC patients, incidence of EGFR mutation varies from 2% to 13%.8, 9 According to the updated CAP/IASLC/AMP Molecular Testing guideline, EGFR testing is recommended for adenocarcinomas and mixed lung cancers with an adenocarcinoma component in the setting of lung cancer resection specimens." (PMID 32667739, 2020). "Furthermore, the signal intensity of lung cancer cells that overexpressed EGFR and were targeted with anti-EGFR-PEG-SPIO decreased more significantly than in the PEG-SPIO (non-targeting NPs) group." (PMID 33198090, 2020). "This diagnostic/prognostic study proposes a clinically applicable large-scale bidirectional generative adversarial network for predicting the efficacy of epidermal growth factor receptor–tyrosine kinase inhibitor therapy in patients with non–small cell lung cancer." (PMID 33331920, 2020). "Since the discovery of actionable activating epidermal growth factor receptor (EGFR) mutation and anaplastic lymphoma kinase (ALK) rearrangement in lung cancer, thoracic oncologists have led the way in comprehensive genomic profiling (CGP) of solid malignancies for precision medicine." (PMID 32478891, 2020). "In the lung cancer cell lines, the moderate EGFR expression exceeded clearly the EpCAM expression." (PMID 32504247, 2020). "Given that EGFR-mutant lung tumors are heterogeneous, an individual EGFR-mutant lung cancer patient in theory may have subclones that are disposed to EMT and others that are disposed to SCLC." (PMID 32292420, 2020). "However, few studies have investigated DNA methylation changes in EGFR wild type lung cancers with low PD-L1 expression." (PMID 32899191, 2020). "EGFR mutations are the most commonly occurring driver mutations in non-small cell lung cancer (NSCLC) with adenocarcinoma histology, which accounts for over 80% of all lung cancer." (PMID 31940362, 2020). "However, the results from an American research team indicated that METTL3 can increase the invasiveness of lung cancer cells by initiating the translation of oncogenes (EGFR, TAZ, and MAPKAPK2)." (PMID 32175271, 2020). "Furthermore, BASP1 decreases the drug sensitivity of lung cancer cells treated with EGFR tyrosine kinase inhibitors (TKIs) (erlotinib and afatinib)." (PMID 33042262, 2020). "Thus, EGFR mutations are one of the driving forces of lung tumorigenesis, making lung cancer cells dependent on the EGFR signaling for growth and survival." (PMID 32429547, 2020). "Studies have shown significant differences in mutation patterns and frequencies of KRAS and EGFR genes between smokers and never smokers with lung cancer." (PMID 33381603, 2020). "Furthermore, EGFR gene amplifications or mutations are found in e.g., HNSCC, lung cancer or glioblastoma (GBM), driving carcinogenesis and tumor progression." (PMID 32903756, 2020).